TFPT (TCF3 fusion partner)
Description:
Putative regulatory component of the chromatin remodeling INO80 complex which is involved in transcriptional regulation, DNA replication and probably DNA repair.
Synonyms: INO80F; FB1; amida
Tractability: PROTAC: UniProt records ubiquitination sites on it; ubiquitination databases record sites on it.
Gene: Protein-coding gene on chromosome 19 (54,107,020 to 54,115,657, reverse strand). Ensembl gene ENSG00000105619.
Subcellular location: Nucleus
Subcellular location (Human Protein Atlas): Nucleoplasm
Pathways (Reactome):
DNA Repair: DNA Damage Recognition in GG-NER
Metabolism of proteins: UCH proteinases
Gene Ontology:
Molecular function: protein binding; DNA binding
Biological process: apoptotic signaling pathway; chromatin remodeling; positive regulation of DNA-templated transcription; regulation of cell cycle; regulation of chromosome organization; regulation of DNA replication; regulation of DNA strand elongation; positive regulation of apoptotic process; apoptotic process; positive regulation of DNA repair; positive regulation of telomere maintenance in response to DNA damage; regulation of DNA repair; regulation of embryonic development; telomere maintenance
Cellular component: Ino80 complex; nucleoplasm; cytoplasm; nucleus
Genetic constraint (gnomAD): Loss-of-function variants: 27 observed, 29.39 expected, observed/expected ratio (o/e) 0.92, 90% interval 0.68 to 1.27. The upper end of that interval is the gene's LOEUF score, 1.27, which puts it in group 5 of 6, group 1 being the genes least tolerant of losing a copy. Missense variants: 330 observed, 342 expected, observed/expected ratio (o/e) 0.96, 90% interval 0.88 to 1.06. Synonymous variants: 152 observed, 140.15 expected, observed/expected ratio (o/e) 1.08, 90% interval 0.95 to 1.24.
Homologues: Orthologues: chimpanzee TFPT (100% identical), macaque TFPT (99% identical), pig TFPT (98% identical), dog TFPT (95% identical), guinea pig TFPT (92% identical), rat Tfpt (91% identical), mouse Tfpt (91% identical), rabbit TFPT (88% identical), tropical clawed frog tfpt (57% identical).
Diseases named in the same sentence as TFPT in open-access papers:
TFPT is named in the same sentence as 30 diseases in open-access papers, as found by Europe PMC text mining. Sharing a sentence is not in itself a finding about the gene and the disease. The quoted sentences say what the papers report.
leukemia (1 paper, 2022). A malignant (clonal) hematologic disorder, involving hematopoietic stem cells and characterized by the presence of primitive or atypical myeloid or lymphoid cells in the bone marrow and the blood. "TFPT (FB1), the nearest one adjacent to PRPF31, is reported to be related to development of leukemia, acting as a molecular fusion partner of TCF3 (E2A)." (PMID 36431159, 2022).
psychosis (1 paper, 2024). "In our systematic review with broad inclusion criteria, we found only 17 studies of TFPT in psychosis, with the literature largely comprised of case series." (PMID 38441953, 2024).
cancer (7 papers, 2010 to 2025). A tumor composed of atypical neoplastic, often pleomorphic cells that invade other tissues. "For example, the deletion of the chromosome 16, the 19q13.2–19q13.43 regions, and the chromosome 21 are significantly correlated with underexpression of candidate cancer-suppressor genes, respectively CBFB or CDH11, TFPT and DSCR1, giving additional evidence in support of these events." (PMID 20711339, 2010).
tumor (6 papers, 2014 to 2022). "By categorizing tumor-specific CNA regions in metastases, we found that alterations of oncogenes and tumor suppressors, for instance, tumor suppressor PMS2 and oncogenes TFPT, ZNF331, and others, may be linked to metastatic progression." (PMID 24405831, 2014).
neurodevelopmental disorder (1 paper, 2020). A behavioral and cognitive disorder with onset during the developmental period that involves impaired or aberrant development of intellectual, motor, or social functions. "Other genes, such as GMIP, NEK1, TFPT, CELSR3, and TTC21A, also showed interactions with ASD or other neurodevelopmental disorder-related genes in each gene network in the previous studies." (PMID 33374967, 2020).
TFPT also shares sentences with these, for which no sentence is quoted: infection (7 papers); esophageal cancer (6); neural tube defect (3); liver cancer (2); acute lymphoblastic leukemia (1); animal diseases (1); bacterial infection (1); breast carcinoma (1); cardiovascular disease (1); colon adenocarcinoma (1); E. coli infections (1); edema (1); fungal infection (1); glioma (1); hepatocellular carcinoma (1); immune dysfunction (1); immunotoxicity (1); kidney cancer (1); kidney inflammation (1); kidney tumors (1); mycotoxicosis (1); neuroblastoma (1); pulmonary edema (1); renal carcinoma (1); renal fibrosis (1).